IGF2BP1 (insulin like growth factor 2 mRNA binding protein 1)
Diseases named in the same sentence as IGF2BP1 in open-access papers (continued):
Sharing a sentence is not in itself a finding about the gene and the disease.
glioma (continued). "For example, MAGEA6-AMPK signaling is activated by knock-out IGF2BP1 with CRISPR/Cas9, resulting in the apoptosis of glioma cells (A172) and inhibiting the survival of human glioma cells, so as to achieve a therapeutic effect." (PMID 36672345, 2023). "By modulating the miR-526b-3p/IGF2BP1/MAPK signaling, LINC00689 silencing inhibits glioma tumorigenesis in vivo." (PMID 38072944, 2023). "Significantly, Lnc-THOR silencing/KO or IGF2BP1 KO induced MAGEA6 degradation (both mRNA and protein), AMPKα1 protein accumulation, and AMPK activation in A172 glioma cells." (PMID 31727877, 2019). "Results demonstrated that the IGF2BP1 protein is co-precipitated with the in vitro-transcribed biotinylated Lnc-THOR (provided by Dr. Wang39) in both A172 cells and primary human glioma cells (“Pri-1/-2”)." (PMID 31727877, 2019). "LncRNA PART1 can suppress glioma proliferation and migration via miR-374b/SALL1 axis, LINC00689 can inhibit glioma tumorigenesis via the miR-526b-3p/IGF2BP1 axis, GAS5 can alter the EMT process, proliferation, migration, and invasion of glioma cells through miR-106b targeting PTEN." (PMID 36425564, 2022). "Twenty-two vital RBPs, IGF2BP1, IGF2BP3, EIF4A3, hnRNPC, and AGO2, can bind to circRNAs and may play important biological functions in glioma." (PMID 33323543, 2020). "In addition to IGF2BP1, inhibition of IGF2BP2 increases the sensitivity of glioma cells to TMZ." (PMID 40469294, 2025). "Furthermore, IGF2BP1 is targeted by various non-coding RNAs and microRNAs, such as LINC00689, PCAT6, Lnc-THOR, and miR-4500, which regulate its expression and thus impact glioma progression and apoptosis." (PMID 38474421, 2024). "Therefore, IGF2BP1 is important for MAGEA6 expression and AMPK inactivation in glioma cells." (PMID 31727877, 2019).
neuroblastoma (15 papers, 2015 to 2025). Neuroblastoma (NB) is the most common solid, extracranial childhood tumor. "IGF2BP1 upregulation in neuroblastoma was associated with lower overall survival and positively correlated with MYCN mRNA, even in patients with MYCN-non-amplified tumors." (PMID 38730633, 2024). "IGF2BP1 is upregulated in higher-risk clinical neuroblastoma groupings, including MYCN-amplified (MNA) or INSS-4 (International Neuroblastoma Staging System) tumors." (PMID 37246217, 2023). "We demonstrated that IGF2BP1 modulates MYCN expression in neuroblastoma cell models, but the underlying mechanisms and potential synergy of both in promoting HRN remained elusive." (PMID 37246217, 2023). "IGF2BP1-driven malignancies are reminiscent to human high-risk neuroblastoma, including 2p/17q-syntenic chromosomal gains and upregulation of Mycn, Birc5, as well as key neuroblastoma circuit factors like Phox2b." (PMID 37246217, 2023). "Public neuroblastoma single cell RNA-seq data indicated nearly exclusive expression and strong association of IGF2BP1 and MYCN expression in tumor cell populations." (PMID 37246217, 2023). "Another 17q gained candidate gene, IGF2BP1, was reported to associate with poor neuroblastoma outcome." (PMID 37246217, 2023). "In neuroblastoma, chromosomal gains at chromosome 17q, including IGF2BP1, and MYCN amplification at chromosome 2p are associated with adverse outcome." (PMID 37246217, 2023). "This further supports the previously proposed prognostic value of IGF2BP1 in neuroblastoma, as observed here in low- and high-risk subgroups except MNA." (PMID 37246217, 2023). "Moreover, IGF2BP1 was also regarded as a risk factor in neuroblastoma." (PMID 35519620, 2022). "Consistent with our findings in MM cells with 1q+, the proliferation of neuroblastoma cells can also be inhibited by either knocking down IGF2BP1 expression or treatment with the inhibitor BTYNB." (PMID 39534570, 2024). "Chromosomal 17q21-ter is commonly gained in neuroblastoma, where the insulin-like growth factor-2 mRNA-binding protein 1 (IGF2BP1) gene is located (17q21.32)." (PMID 38730633, 2024). "This is evidenced by chromosomal misbalance reminiscent of human neuroblastoma in MYCN- as well as IGF2BP1-driven neuroblastoma mouse models." (PMID 37246217, 2023). "We reveal a novel, druggable feedforward loop of IGF2BP1 (17q) and MYCN (2p) in high-risk neuroblastoma." (PMID 37246217, 2023). "The genomic landscape of MYCN/IGF2BP1-induced neuroblastoma was analyzed by sWGS performed on AGM, TI, TIM and murine wildtype adrenal glands." (PMID 37246217, 2023). "Our studies provide the first evidence that IGF2BP1 is a potent and druggable oncogene in neuroblastoma, with target prospects in other MYC/N-driven malignancies." (PMID 37246217, 2023). "Irrespectively, R26IGF2BP1/MYCN and R26IGF2BP1/IGF2BP1 neuroblastoma show strikingly similar gene expression, most prominently induction of E2F/DREAM-controlled CC genes." (PMID 37246217, 2023). "In neuroblastoma cell and xenograft models, IGF2BP1 deletion and inhibition by the small molecule BTYNB impair tumor growth." (PMID 37246217, 2023). "BTYNB decreased neuroblastoma cell viability, as previously reported, disturbed MYCN mRNA association with IGF2BP1 and impaired MYCN at only modest reduction of IGF2BP1." (PMID 37246217, 2023). "The insulin-like growth factor 2 mRNA-binding protein 1 (IGF2BP1) is an oncofetal RNA-binding protein with reported gene gain and suggested MYCN-associated roles in neuroblastoma." (PMID 37246217, 2023). "Conditional, sympatho-adrenal transgene expression of IGF2BP1 induces neuroblastoma at a 100% incidence." (PMID 37246217, 2023). "In neuroblastoma, IGF2BP1 synergizes with MYCN by transcriptional/post-transcriptional feedforward regulation, which unleashes an oncogene storm and genomic instability reminiscent of high-risk diseases." (PMID 37246217, 2023).
neuroblastoma (continued). "In sum, this suggested that IGF2BP1 is a potent, druggable oncogene in neuroblastoma synergizing with MYCN in a transcriptional/post-transcriptional feedforward loop resulting in the upregulation of oncogenes like the 17q-located BIRC5." (PMID 37246217, 2023). "Here, we demonstrate that down-regulation of IGF2BP1 activity, either by transcript silencing or chemical inhibition, suppresses neuroblastoma cell growth." (PMID 33796454, 2021). "In neuroblastoma, IGF2BP1 was shown to be expressed at high levels in stage 4 tumors, and associated with overall lower patient survival." (PMID 33796454, 2021). "This likely is of pivotal importance in MNA neuroblastoma, where IGF2BP1 probably serves as a MYCN-driven antagonist of MYCN-inhibitory miRNAs upregulated in MNA neuroblastoma." (PMID 34026620, 2021). "IGF2BP proteins have been reported to influence the sensitivity of chemotherapeutics, as for instance demonstrated in neuroblastoma cell lines, where IGF2BP1 promotes resistance towards doxorubicin." (PMID 33829040, 2021). "Taken together, these findings suggest that many cancer-related proliferation-promoting pathways are altered by IGF2BP1 depletion in neuroblastoma." (PMID 33796454, 2021). "Conversely, mRNA transcripts associated with cell mortality and apoptosis were both enhanced, suggesting that IGF2BP1 plays an important role in promoting oncogenesis in neuroblastoma." (PMID 33796454, 2021). "Our findings provide strong evidence that enforced expression of MYCN in MNA neuroblastoma essentially relies on IGF2BP1." (PMID 34026620, 2021). "The SK-N-DZ cell line represents high-risk neuroblastoma, with abundant expression of MYCN and IGF2BP1." (PMID 33796454, 2021). "On the contrary, IGF2BP1 upregulation in MNA neuroblastoma is supported by previous studies in primary tumors, MYC/MYCN-driven transcriptional regulation and conserved oncofetal expression of the protein." (PMID 34026620, 2021). "In this study, we demonstrate that down-regulation of IGF2BP1 activity, either by transcript silencing or chemical inhibition, suppresses neuroblastoma cell growth." (PMID 33796454, 2021). "Expression of the oncofetal IGF2BP1 is upregulated in MNA neuroblastoma, promotes MYCN protein and RNA expression, and is considered a potent and conserved inhibitor of miRNA-dependent downregulation of oncogenic factors in cancer." (PMID 34026620, 2021). "In the 69 neuroblastoma tissues, IGF2BP1 DNA copy number, mRNA, and protein abundance were strikingly higher in stage 4 than stage 1 tumor." (PMID 29954406, 2018). "In addition, recent studies revealed a role of IGF2BP1 in promoting neuroblastoma metastasis via extracellular vesicles guiding SEMA3A and SHMT2 expression." (PMID 37246217, 2023). "Here, we reveal that IGF2BP1 is a bona fide druggable oncogene in neuroblastoma." (PMID 37246217, 2023). "In view of MYC/N similarity and strongly associated expression of IGF2BP1 and MYCN in neuroblastoma, we hypothesized that MYCN promotes IGF2BP1 transcription as well." (PMID 37246217, 2023). "Our findings suggested, IGF2BP1 as a novel driver of neuroblastoma." (PMID 37246217, 2023). "Thus, deregulated miRNA synthesis and selective impairment of miRNA-directed downregulation of oncogene expression by IGF2BP1 are major mechanisms promoting neuroblastoma initiation and progression." (PMID 37246217, 2023). "Next we attempted to determine whether CDK2 and CDK9 inhibition, when combined with IGF2BP1 inhibition, would have an additive effect on neuroblastoma cell replication." (PMID 33796454, 2021). "Whereas ELAVL4 expression is decreased in MNA neuroblastoma, IGF2BP1 expression is elevated." (PMID 34026620, 2021). "The genes associated with these networks included transcripts associated with tumorgenesis and cell proliferation, leading us to believe IGF2BP1 suppression could result in further sensitization of neuroblastoma to these drugs." (PMID 33796454, 2021).
neuroblastoma (continued). "Whether in combination with conventional chemotherapeutic agents, or CDK inhibitors, we propose that the inhibition of IGF2BP1 function represents a promising novel strategy for future neuroblastoma treatment." (PMID 33796454, 2021). "The important roles of IGF2BP1 in neuroblastoma, meningiomas, and glioblastoma were reported." (PMID 29954406, 2018). "However, it remains unknown if IGF2BP1 is an oncogene in human cancers, how it synergizes with MYCN in neuroblastoma and if the targeting of IGF2BP1 harbors therapeutic benefits in cancer treatment." (PMID 37246217, 2023). "In addition to chemotherapeutic agents more commonly used to treat neuroblastoma, we sought to determine if IGF2BP1 inhibition could be combined with more potent inhibitors of cell proliferation." (PMID 33796454, 2021). "Next to IGF2BP1, this analysis unraveled top-ranking of BIRC5 and TOP2A among common essential as well as NME1 among neuroblastoma essential Chr 17q genes." (PMID 37246217, 2023). "This suggested effective targeting of MYCN/IGF2BP1 by combined BRDi and IGF2BP1i in MNA neuroblastoma." (PMID 37246217, 2023). "MYCN/IGF2BP1 feedback regulation also stimulates LIN28B expression, a strong inducer of neuroblastoma." (PMID 37246217, 2023). "We reveal a novel, druggable neuroblastoma oncogene circuit settling on strong, transcriptional/post-transcriptional synergy of MYCN and IGF2BP1." (PMID 37246217, 2023). "The deletion (KO) of IGF2BP1 consistently reduced MYCN protein and mRNA expression in three neuroblastoma cell lines." (PMID 37246217, 2023). "Strikingly, however, tumor incidence increased to 100% (8/8) and median survival was reduced to 107 d in R26IGF2BP1/MYCN mice, validating a strong synergy of IGF2BP1 and MYCN in promoting neuroblastoma." (PMID 37246217, 2023). "Another prominent cancer-type-specific association found by SuperDendrix is increased dependency on IGF2BP1, a regulator of insulin growth factor receptor IGF1R, in Ewing’s sarcoma and neuroblastoma." (PMID 35382456, 2022). "In the IGF1R pathway, we find increased dependency on IGF2BP1, IGF1R, IRS1, and IRS2 in neuroblastoma, Ewing’s sarcoma, pancreas, myeloma, or rhabdomyosarcoma." (PMID 35382456, 2022). "These include correlations between IGF2BP1 and IGF1R (R = 0.48) in Ewing’s sarcoma and between IGF2BP1 and IRS2 dependencies (R = 0.32) in Ewing’s sarcoma and neuroblastoma." (PMID 35382456, 2022). "To this end, we have investigated two RNA-binding proteins (RBPs), previously reported to control MYCN expression in neuroblastoma, ELAVL4 (HuD) and IGF2BP1." (PMID 34026620, 2021). "Because of the success we observed in combining IGF2BP1 inhibition with commonly used therapeutics, we endeavored to determine whether we could replicate these results with drugs even more efficient at inhibiting neuroblastoma cell proliferation at lower doses." (PMID 33796454, 2021). "Together, this provides strong evidence that IGF2BP1 is a potent miRNA antagonist upregulating MYCN mRNA and protein in neuroblastoma." (PMID 34026620, 2021). "Consistent with the literature, MYCN-amplified neuroblastoma cell lines showed very high levels of N-Myc, MYCNOS, and IGF2BP1 and very low levels of c-Myc RNA expression." (PMID 31690716, 2019). "Their abundance was decreased by IGF2BP1 depletion in human neuroblastoma cells without striking effects on post-translational modifications." (PMID 37246217, 2023). "IGF2BP1 is a post-transcriptional enhancer of oncogene expression, including MYCN and BIRC5, in various cancers with exceeding expression in Chr 17q unbalanced neuroblastoma." (PMID 37246217, 2023). "MYCN/IGF2BP1 synergy also promotes chromosomal gains at 2p and 17q, but retains strong potential also in non-amplified (2p or 17q) neuroblastoma models, e.g. NBL-S." (PMID 37246217, 2023).
neuroblastoma (continued). "Molecular mechanisms and gene expression profiles underlying the oncogenic and therapeutic target potential of the 17q oncogene IGF2BP1 and its cross-talk with MYCN were characterized and validated in human neuroblastoma cells, xenografts and PDX as well as novel IGF2BP1/MYCN transgene mouse models." (PMID 37246217, 2023). "Finally, we evaluate if trans-acting factors, in particular IGF2BP1 and ELAVL4, or a putative miRNA decoy function of the MYCN-3’UTR uncouple increased expression of MYCN-regulatory miRNAs in neuroblastoma from elevated expression of MYCN protein." (PMID 34026620, 2021). "IGF2BP1 clearly influenced MYCN expression and neuroblastoma cell survival." (PMID 29954406, 2018). "Furthermore, the combination of IGF2BP1 inhibition along with commonly used chemotherapeutics that broadly affect DNA synthesis, or cyclin-dependent kinase (CDK) inhibitors that disrupt signal transduction, have a synergistic effect on the suppression of neuroblastoma cell proliferation." (PMID 33796454, 2021). "In view of MYCN/IGF2BP1 feedforward regulation, it was expected that IGF2BP1 alters sensitivity to BRDi and BTYNB (IGF2BP1i) synergizes with BRDi in non-MYCN-translocated neuroblastoma." (PMID 37246217, 2023). "Here our RNA sequencing analysis identifies N-Myc, MYCNOS, IGF2BP1, lncNB1, RNF217, RP11-102F4.3, GRIK3, and SLCO5A1 as the RNAs most considerably over-expressed in MYCN-amplified, compared with MYCN-non-amplified, neuroblastoma cell lines." (PMID 31690716, 2019).
cervical cancer (14 papers, 2016 to 2025). A primary or metastatic malignant neoplasm involving the cervix. "Silencing IGF2BP1 hindered CDR1as-mediated metastasis in cervical cancer." (PMID 37361215, 2023). "Silencing IGF2BP1 hampers CDR1as related metastasis in cervical cancer." (PMID 37004067, 2023). "In addition, GEPIA analysis showed that IGF2BP1/2/3 were up‐regulated in cervical cancer tissues, but only the differential expression of IGF2BP3 was significant." (PMID 37877353, 2023). "For example, in cervical cancer, the TRIM11 mRNA’s stability is enhanced by IGF2BP1 depending on m6A modification, which is mediated by METTL14 and accelerates cervical cancer progression by mediating PHLPP ubiquitination." (PMID 39557826, 2024). "A decrease in the expression levels of IGF2BP1 and IGF2BP2 was also detected in Parkin‐overexpressing cervical cancer cells." (PMID 37877353, 2023). "Considering the complete cervical cancer cohort, IGF2BP1 failed to yield conclusive results in terms of survival probability." (PMID 37515119, 2023). "Furthermore, CDR1as was found to promote the orchestration of IGF2BP1 on the SLUG mRNA and to maintain its stability, thereby contributing to cervical cancer metastasis." (PMID 37361215, 2023). "Furthermore, a slightly elevated, yet not significant, expression of IGF2BP1 RNA was observed in HPV-positive cervical cancer samples deposited by the TCGA (median FPKM = 0.08), and compared to HPV-negative samples (median FPKM = 0.03)." (PMID 37515119, 2023). "IGF2BP1 and IGF2BP2 are also regulated by Parkin, but we did not explore their ubiquitination modification or their role in the tumourigenesis of cervical cancer in the current study." (PMID 37877353, 2023).
glioblastoma (12 papers, 2018 to 2025). The most malignant astrocytic tumor (WHO grade IV). "IGF2BP1, IGF2BP2 and IGF2BP3 are dysregulated in many tumor types, being associated with chemoresistance in glioblastoma, ovarian and colorectal cancer." (PMID 40061896, 2025). "IGF2BP1 is upregulated in mesenchymal glioblastoma compared to proneural glioblastoma, correlating with poor patient outcomes." (PMID 38474421, 2024). "Futhermore, IGF2BP1 has been proved to be a target of miR-873 in glioblastoma cells and their growth and metastasis are inhibited by miR-873." (PMID 31289617, 2019). "In glioblastoma, miR-873-5p repressed IGF2 mRNA-binding protein 1 (IGF2BP1) expression to suppress glioblastoma tumorigenesis." (PMID 34497766, 2021). "In glioblastoma multiforme (GBM), PCAT6 could upregulate IGF2BP1 expression by acting as a ceRNA against miR-513, causing a PCAT6/miR-513/IGF2BP1 positive feedback loop that facilitates GBM progression." (PMID 34327141, 2021). "IGF2BP1 plays a dominant role as an m6A reader and is involved in a variety of cancer processes, such as leukemia, endometrial cancer (EC), BCA, lung adenocarcinoma (LUAD), and glioblastoma (GBM)." (PMID 36226062, 2022). "However, their overexpression was observed to repress the cell proliferation and migration, and invasion of GBM through downregulating the IGF2BP1 levels, which reduces the level of c-MYC, CD44, MKI67, and PTEN mRNA in GBM cells or blocks G1/S transition in glioblastoma cell." (PMID 29954406, 2018).